ACVR1 (activin A receptor type 1)
Diseases named in the same sentence as ACVR1 in open-access papers (continued):
Sharing a sentence is not in itself a finding about the gene and the disease.
tumor (80 papers, 2009 to 2026). "Conversely, there is an increase in Acvr1, Zfp703, Isl1, and Tcf712, suggesting that ephrinB2 loss shifts the tumor microenvironment (TME) toward a less invasive phenotype." (PMID 39489818, 2025). "They should mimic the TME, maintain genetic and epigenetic fidelity (e.g., H3K27M, ACVR1 mutations), and support proper tumor localization for clinical relevance." (PMID 40647519, 2025). "ACVR1 mutation has been found to be associated with an earlier tumor development onset, with a median age of 5 years at diagnosis, and a slightly longer OS (15 months)." (PMID 39941789, 2025). "One tumour harboured a FGFR1MUT in the context of a DMG H3-K27 wild-type with EZHIP overexpression presenting an ACVR1 mutation (case #60)." (PMID 38066305, 2023). "We show that these tumours have recurrent and mutually exclusive mutations in either ACVR1 or EGFR and are characterised by high expression of EZHIP associated to its promoter hypomethylation." (PMID 36882456, 2023). "Four children with DIPG for whom ACVR1 mutations were confirmed in stereotactic tumor biopsy specimens and/or peripheral blood were treated with vandetanib and an mTOR inhibitor." (PMID 34551970, 2022). "A recent study investigated the clonal evolution of H3K27M-mutant DMG and demonstrated ACVR1 mutations alongside H3K27M mutations in the earliest tumor clone, suggesting that ACVR1 mutation is critical for oncogenesis." (PMID 34771443, 2021). "In light of this new information, survival curves were reanalyzed so that only tumor-bearing mice were examined in order to understand the effect of ACVR1 mutations on survival more clearly." (PMID 30833574, 2019). "Collectively these results suggest that together, ACVR1 R206H and H3.1K27M, significantly decrease survival and increase tumor incidence, suggesting a cooperating role for both mutations in tumor initiation." (PMID 30833574, 2019). "The specific association of ACVR1 mutations with DIPG tumours suggests a direct link to neurodevelopment and highlights the encoded bone morphogenetic protein receptor kinase ALK2 as a promising drug target." (PMID 31551357, 2019). "Sanger sequencing of DNA taken from the NGT16 cell line showed H3K27M mutation of HIST1H3B and ACVR1, confirming that mutations which were present in the primary tumor were also present in the cell line." (PMID 32039031, 2019). "The rather unique association of ACVR1 mutations with DIPG tumours highlights this growth factor receptor as a promising target for future clinical investigation." (PMID 31551357, 2019). "Of note, mutant ACVR1 occurs ubiquitously throughout these DIPG tumours suggesting that mutant ACVR1 is an early and obligate partner of H3K27M mutations during clonal evolution." (PMID 31551357, 2019). "Taking the ACVR1 mutations separately, tumours with R258G trended towards fewer copy number aberrations (p = 0.0658, t-test), whilst R206H had significantly fewer somatic mutations (0.0257, t-test)." (PMID 31098401, 2019). "The glutamic acid (E) peak for ACVR1 was very small, suggesting that only a proportion of the cultured tumor cells harbored the ACVR1 G328E mutation, consistent with data obtained from biopsy samples in a previously published study." (PMID 32039031, 2019). "Nonetheless, as ACVR1 mutations facilitate early tumor propagation in conjunction with other molecular aberrations, they represent novel targets for future therapies." (PMID 28401062, 2017). "Disease-defining somatic mutations in H3F3A, HIST1H3B, and ACVR1 were conserved across all tumor locations, as were mutations affecting the (RTK)-PI3K-MAPK pathway." (PMID 26727948, 2016).
tumor (continued). "Activating point mutations of ACVR1, present in 20–30 % of DIPGs and potentially targetable, were also conserved across all tumor compartments." (PMID 26727948, 2016). "None of the PDGFRA gains/amplifications, PIK3CA mutations, ALT phenotype or ACVR1 mutations were found in tumours with PNET histology." (PMID 25047029, 2014). "Furthermore, the H3-WT tumours with ACVR1 mutations had higher expression levels of EZHIP than H3-WT tumours with EGFR mutations." (PMID 36882456, 2023). "High TNC expression in DIPG may therefore be due to the downstream effects of H3K27 M and ACVR1 mutations, while its effect on tumor formation may be influenced by the tumor microenvironment in the developing brainstem relative to the cerebral hemispheres." (PMID 31092287, 2019). "Additionally, the combination of ACVR1 R206H and H3.1K27M increases tumor incidence, suggesting that these mutations play a role in tumor initiation." (PMID 30833574, 2019). "Somatic mutations in ACVR1 are almost exclusively limited to DIPG with reports by the Catalogue of Somatic Mutations in Cancer highlighting ACVR1 variants as present in only 0.3% of all tumor types." (PMID 28401062, 2017). "Both areas carried HIST2H3C/ACVR1 mutations inferred to occur early in tumour evolution." (PMID 27048880, 2016). "However, the astrocytic phenotype was observed in the H3.1-mutated tumours independently of the ACVR1 mutation and future work in vitro should help unravel this matter." (PMID 26399631, 2015). "FOP is a very rare condition caused by germline variants in the gene encoding activin A receptor type 1 (ACVR1) and is associated with progressive heterotopic extraskeletal ossification, which may present as tumor-like masses typically in the shoulder and back areas, on the scalp or head." (PMID 32888134, 2021). "Furthermore, H3.3K27M can substitute for H3.1K27M mutation and cooperate with ACVR1 R206H in tumor initiation as mice that were infected with ACVR1 R206H, H3.3K27M, Cre, and PDGFA also had a high tumor incidence (20/22 = 91%) similar to ACVR1 R206H, H3.1K27M, Cre, and PDGFA." (PMID 30833574, 2019). "Importantly, tumor cells harboring ACVR1 mutations are inhibited by ALK2 inhibitors." (PMID 30279357, 2018). "It has been suggested that the gene expression signature may not be due to the specific histone mutation, but rather the accompanying alterations (PDGFRA vs. ACVR1), supporting the notion that modulation of the microenvironment by tumour cells is more influential than the histone mutation." (PMID 30453529, 2018). "Administration of an ACVR1 inhibitor during the coculture of 2DOs and mouse stromal cells inhibited tumor growth." (PMID 40745121, 2025). "In conclusion, this study demonstrated that ACVR1 is a potential therapeutic target that inhibits the proliferation of CAFs and ACVR1-positive stromal cells in advanced tumor stroma adjacent to tumor cells." (PMID 40745121, 2025). "The significantly higher frequency of NF1, ACVR1, MAP2K1, and AKT1 mutations in EOCRC H/L patient data support the call for expanded investigation into their biological significance in tumor development and treatment response." (PMID 40227607, 2025).
tumor (continued). "Bioinformatic analyses indicate that BMP signaling pathway activation ground state is independent of ACVR1 status in pDMG, which likely results both from BMP2/7 tumor-autonomous and microenvironment-driven signals in ACVR1 WT tumors." (PMID 39373720, 2024). "INHBA on SPP1+ macrophages is predicted to interact with ACVR1 on tumor cells, targeting downstream genes, including SERPINE1 and SMAD3, which positively regulate cyclin-dependent protein kinase activity." (PMID 38519500, 2024). "These HSJD-DIPG-007 tumour cells harbour mutations in H3F3A K27M, ACVR1 R206H, PPM1Dp.P428fs, and PIK3CAp.H1047R." (PMID 36831063, 2023). "Although we report a trend for H3-WT ACVR1-mutant tumours to express higher levels of EZHIP, our cohort size is too small for this observation to reach statistical significance and a larger cohort would be required to confirm our findings." (PMID 36882456, 2023). "ACVR1 and EGFR mutations were mutually exclusive with tumours clustering distinctly by both RNA expression and DNA methylation t-SNE plots, suggesting even further sub-classification within this subgroup." (PMID 36882456, 2023). "This combination was well tolerated in vivo and significantly extended survival and reduced tumor burden in an orthotopic ACVR1-mutant patient-derived DIPG xenograft model." (PMID 34551970, 2022). "All processes involved in tumor neo-angiogenesis, and the mechanisms of action in tumor cell proliferation, involve the ACVR1 and TSPAN3 genes, which are target genes for miR-197 and the IGFBP5 receptor." (PMID 36143221, 2022). "The primary DIPG human cell line HSJD-DIPG-007 highly represents this pediatric tumor, displaying the most prevalent DIPG mutations, H3F3A (K27M) and ACVR1 (R206H)." (PMID 36293329, 2022). "Many studies had shown that ACVR1 is an important tumour suppressor participating in the biological processes of cancer cells like proliferation, migration, invasion, metastasis and apoptosis." (PMID 33354912, 2021). "Along with common mutations such as ACVR1 and H3 K27M found in DIPG, 50% of DIPG cases harbor gain of function processes that stimulate tyrosine kinase receptors to trigger further tumor progression." (PMID 33168005, 2020). "In a previous study, the HSJD-DIPG-007 tumor cell line showed the expression of the histone variant H3F31 (H3.3), K27M-mutated protein (H3K27M), and the ACVR1 mutation, previously defined as the hallmark mutations in DIPG." (PMID 32349240, 2020). "Our experiments confirmed the inhibition effects of several TβRI inhibitors on ACVR1 wild-type and G328V mutant patient tumor derived DIPG cell lines at 20–50 μM doses." (PMID 32273545, 2020). "The addition of the PDGFA ligand in the presence of Acvr1-R206H and H3.1-K27M increased the tumour occurrence." (PMID 31683698, 2019). "DNA sequencing of the tumor revealed the H3K27M mutation in HIST1H3B (left), a rare mutation variant in histone, and G328E mutation in ACVR1 (right), a frequently encountered mutation in patients with DIPGs with HIST1H3B mutation." (PMID 32039031, 2019). "Together, our results demonstrate that ACVR1 R206H and H3.1K27M promote tumor initiation, accelerate gliomagenesis, promote a mesenchymal profile partly due to Stat3 activation, and identify LDN212854 as a promising compound to treat DIPG." (PMID 30833574, 2019).
tumor (continued). "Additionally, elevated expression of ACVR1 was observed in the stroma adjacent to the advanced regions of the tumor compared to that in the normal colon epithelium." (PMID 40745121, 2025). "In other words, H3.1K27M tumors would depend on the concomitant acquisition of the ACVR1 mutation for transformation, whereas the BMP pathway could be activated in a tumor-independent manner in H3.3K27M tumors, due to their BMP-rich microenvironment." (PMID 39373720, 2024). "Of note, the other ACVR1-mutated case did not match with any group (zcc120), as well as the H3-WT tumour with low EZHIP expression (zcc446), emphasising the potential for further classification refinement." (PMID 36882456, 2023). "ACVR1 correlated with better OS in our study but should be regarded as a complex regulator of cancer biology, because ACVR1 could act as a tumor suppressor or oncogene, depending on the type of cancer or cell, or ligand involved." (PMID 34036102, 2021). "Inhibition of both MEK1/2 and mutant ACVR1 suggested that E6201 may show activity against DIPG tumor cells." (PMID 32142668, 2020). "Indeed, ACVR1 mutant tumor tissue had significantly increased phosphorylated STAT3 Y705 levels as compared to their normal brain tissue counterparts." (PMID 30833574, 2019). "However, in combination with PDGFA signaling, ACVR1 R206H and H3.1K27M significantly decrease survival and increase tumor incidence." (PMID 30833574, 2019). "Identification of co-segregation of ACVR1 mutation and dysregulation in the PI3K pathway potentially points the way towards combinatorial approaches which may be tested in this subgroup of tumours." (PMID 31098401, 2019). "In the present study, we demonstrate ACVR1 mutations confer abnormal ligand responsiveness to activin A in DIPG cells, with spatiotemporal expression of activin A in neurodevelopment correlating with tumour origins." (PMID 31098401, 2019). "Lastly, we identify the BMP signaling pathway as a potential effective therapeutic strategy to treat ACVR1 R206H mutant DIPGs as exogenous Noggin expression at tumor initiation or treatment with LDN212854 significantly increases tumor latency and prolongs survival." (PMID 30833574, 2019). "Still, the gene expression signature between H3.1 and H3.3 subgroups may not be due to the H3 mutations themselves but rather the accompanying alterations (PDGFRA vs. ACVR1) or differential modification of the microenvironment by tumour cells." (PMID 26399631, 2015). "By analyzing the expression of BMP effectors in pDMG tumors and patient-derived DIPG models, we propose that the activation of this pathway in ACVR1 WT H3.3K27M tumors could be at least partially mediated by two complementary tumor-autonomous and microenvironment-dependent mechanisms." (PMID 39373720, 2024). "However, while the pro-tumorigenic activity of BMP signaling is clear in ACVR1 mutant pDMG, recent data have unexpectedly reported that BMP ligands may exert a tumor-suppressive activity in H3.3K27M-ACVR1 wild-type (WT) pDMG cellular models." (PMID 39373720, 2024).
tumor (continued). "Based on the potential cross-talk between ACVR1 and TβRI pathways and known and predicted off-targets of ACVR1 inhibitors, we further validated the inhibition effects of several TβRI inhibitors on ACVR1 wild-type and G328V mutant patient tumor derived DIPG cell lines at 20–50 μM doses." (PMID 32273545, 2020). "Very interestingly, mutant Acvr1 (R206H, G328V, G328E) alone did not cause tumours in mouse models." (PMID 31683698, 2019). "However, similar to the dual role of BMPs, ACVR1 could act as a tumour suppressor or oncogene, depending on the cancer type, cell type, or ligand involved." (PMID 31683698, 2019). "Therefore, ACVR1 was proposed as a potential tumour suppressor for eye lens tumours." (PMID 31683698, 2019). "Knocking out PGC specification inducers (ACVR1, SMAD5, PRDM1, or SOX17) or fate-maintaining genes (NANOG or DDX4) suppressed both SPLC and tumor initiation." (PMID 42291258, 2026). "Importantly, ACVR1 mutant diseases have previously been responsive to the retinoic receptor agonist palovarotene, with efficacy repeated in a small cohort of DMG patients, whereby the one patient harboring an ACVR1 mutation experienced tumor stabilization for 30 weeks." (PMID 38525424, 2024). "It is particularly interesting to observe that the deletion of ACVR1, which is regulated by PRC2, almost completely abolished the anti‐tumor efficacy of PRC2 inhibitors in xenograft model." (PMID 38229201, 2024). "The probability of interaction between tumor cells and fibroblast receptor-ligand pairs was higher than that of thyroid cells, especially in TGFB1/ACVR1/TGFBR1, FGF18/FGFR1, BTC/EGFR, BMP8A/BMPR1A/BMPR2, and BMP8A/BMPR1A/BMPR2." (PMID 37733241, 2023). "used this model to develop a murine brainstem pHGG tumor using H3K27M and ACVR1-G328V genetic alterations, along with NRAS and shp53 as oncogenic drivers." (PMID 35978801, 2022). "We particularly found that this agent, which readily crosses the BBB, can significantly decrease tumor volumes, ADC values, MVD, and HNA, c-MET and ACVR1 protein expressions, compared to untreated tumors, as well as significantly increase apoptosis." (PMID 33168005, 2020). "Therefore, we hypothesized that ACVR1 R206H might have an effect on tumor incidence." (PMID 30833574, 2019). "In conclusion, this study highlights the role of mutant ACVR1 and H3.1K27M in tumor initiation and identifies the BMP pathway, particularly LDN212854, as a promising therapeutic agent for further evaluation in ACVR1 mutant DIPG." (PMID 30833574, 2019). "Mutations in previously undiscovered oncogenes, histone H3, and ACVR1, molecular subtypes of DIPG, and the rediscovered role for biopsy for this tumor entity are redefining what is clinically possible in treating these patients." (PMID 26175967, 2015). "Another limitation is that, while the study demonstrated that administering an ACVR1 inhibitor during the coculture of 2DOs and mouse stromal cells inhibited tumor growth, it did not investigate the dynamics of gene expression in the CAFs and 2DOs." (PMID 40745121, 2025). "Integration of all these data unveiled that the BMP-responsive (i.e. High PROGENy TGF-β/BMP score) pool of tumor cells correlates significantly with BMP receptors expression, in particular to BMPR2, BMPR1B, BMPR1A, and ACVR1 levels, respectively in 8, 5, 5, and 4 out of 10 samples." (PMID 39373720, 2024).